RNU7-13P (RNA, U7 small nuclear 13 pseudogene)
Synonyms: U7.13
Gene: Small nuclear RNA gene on chromosome 1 (184,821,428 to 184,821,489, reverse strand). Ensembl gene ENSG00000252222.
Homologues: Orthologues: macaque U7 (84% identical). Paralogues in human: RNU7-8P (95% identical), RNU7-11P (94% identical), RNU7-6P (94% identical), RNU7-28P (92% identical), RNU7-41P (92% identical), RNU7-45P (92% identical), RNU7-18P (90% identical), RNU7-22P (90% identical), RNU7-25P (90% identical), RNU7-3P (90% identical), RNU7-26P (89% identical), RNU7-2P (89% identical), and 142 more.